CDH17 (cadherin 17)
Diseases named in the same sentence as CDH17 in open-access papers (continued):
Sharing a sentence is not in itself a finding about the gene and the disease.
colorectal cancer (continued). "CDH17-mediated integrin activation was observed to mainly affect adhesion and proliferation in colorectal cancer, while VE-cadherin RGD motifs also affected invasion in melanoma and breast cancer cells." (PMID 27966446, 2017). "α2β1 integrin can directly interact with CDH17 through its RGD motif, which causes β1 integrin activation and signaling to induce focal adhesion kinase and Ras activation, leading to colorectal cancer cells proliferation and liver metastasis." (PMID 27765911, 2016). "CDH17 modulated integrin activation and signaling to induce specific focal adhesion kinase and Ras activation, which led to the increase in colorectal cancer cell adhesion and proliferation." (PMID 24465527, 2014). "CDH17 overexpression has been reported in gastric adenocarcinoma, hepatocellular carcinoma and colorectal carcinoma." (PMID 23554857, 2013). "In colorectal cancer, CDH17 expression declines at early stages and is re-expressed at late stages." (PMID 40595509, 2025). "Similar to CDH17, it is significantly overexpressed in colorectal cancer and is distributed across the apical membrane and basolateral membrane of tumor cells, disrupting the tight junctions of the tumor cells, which is beneficial for interaction with targeted therapies." (PMID 40721409, 2025). "Specifically, cadherin-17 (CDH17), known as liver–intestine cadherin or human peptide transporter-1, is implicated in tumor invasion and metastasis, and its high expression in tumor tissues correlates with poor prognosis in patients with colorectal cancer." (PMID 39994505, 2025). "We first investigated total and plasma membrane expression of CDH6 and CDH17, together with α2β1 and αIIbβ3 integrins, in different ovarian and renal cancer cell lines, using the HT29 colorectal cancer cell line as positive control for expression of CDH17 and α2β1 integrin." (PMID 33715292, 2021). "In colorectal cancer, we have confirmed the interaction of CDH17 with α-, β-, and p120-catenins." (PMID 31324051, 2019). "Galectin 3, which was found to cluster with CDH17 in pancreatic ductal adenocarcinoma, is involved in the canonical Wnt/β-catenin signaling pathway and in the accumulation of nuclear β-catenin in colorectal cancer." (PMID 31324051, 2019). "Although there are very few data about the relationship between CDH17 expression and proteins involved in the regulation of Ca2+ levels, it is noteworthy that a number of alterations in these proteins have been routinely observed in colorectal cancer metastasis." (PMID 31324051, 2019). "Regarding gene expression regulation, an analysis of the microRNA (miRNA) expression in the highly metastatic colorectal cancer cell line KM12SM, indicated that three miRNAs (miR-424-3p, -503, and -1292), overexpressed in the metastatic cells, caused an increased expression of CDH17." (PMID 31324051, 2019). "In this regard, the significant homology between CDH17 and L1CAM RGD motifs would suggest a simultaneous blocking of both activities by the RGD-specific monoclonal antibodies in colorectal cancer." (PMID 41039222, 2025). "We also found that CDH17 and GUCY2C were co-high expressed in most colorectal cancer patients and rectum adenocarcinoma patients." (PMID 40721409, 2025). "In colorectal cancer (CRC), higher levels of CDH17 correlate with higher tumour grades and lymphatic invasion, and, in pancreatic tumours (PC), it is linked to dedifferentiation and poor survival." (PMID 41155133, 2025). "For example, cadherin 17 (CDH17) and guanylate cyclase 2C (GUCY2C) are highly expressed in colorectal cancer but have very low expression in normal tissues." (PMID 40057807, 2025). "Our data further support that CDH17, GPA33, and SATB2 in addition to CDX2 are all very sensitive markers for colorectal cancer metastases, and slightly more sensitive than CK20." (PMID 37349623, 2024).
colorectal cancer (continued). "Cadherin-17 (CDH17), a marker of differentiation in intestinal cells, binds and activates α2β1 integrin to promote cell adhesion and proliferation in colorectal cancer (CRC) metastasis." (PMID 38263178, 2024). "The most sensitive markers for GI origin were GPA33 (positive in 98%, 60%, and 100% of pulmonary metastases from colorectal cancer, pancreatic cancer, and other GI adenocarcinomas, respectively), CDX2 (99/40/100%), and CDH17 (99/0/100%)." (PMID 37349623, 2024). "However, using the same functionalization strategy, our nanorods could be conjugated with different antibodies for different EV surface markers such as EpCAM, which is overexpressed in many types of cancers or claudin 1,7, and Cadherin-17, which are specific for colorectal cancer." (PMID 36514065, 2022). "Recent studies have shown that CDH17 is more sensitive than CK20 and CDX-2 in the diagnosis of colorectal cancer." (PMID 28969003, 2017). "The combination of CDH17 and SATB2 had high sensitivity in colorectal cancer with medullary features." (PMID 28969003, 2017). "CDH17 activates the α2β1 integrin pathway through specific RGD motifs to promote cell adhesion, proliferation and liver colonization in colorectal cancer metastasis." (PMID 27966446, 2017). "Both CDH17 and GUCY2C are highly expressed in colorectal cancer." (PMID 40721409, 2025). "The reason to explain this phenomenon is that the interaction between CDH17 and α2β1 integrin is cell type dependent, which specifically exists in colorectal cancer cells, but not in gastric cells." (PMID 24465527, 2014).
hepatocellular carcinoma (17 papers, 2013 to 2025). A malignant tumor that arises from hepatocytes. "In hepatocellular carcinoma, CDH17 loss was also associated with Wnt inhibition, though using distinct mechanisms." (PMID 40595509, 2025). "Cadherin-17 (CDH17) is an oncofetal molecule associated with poor prognostic outcomes of hepatocellular carcinoma (HCC), for which the treatment options are very limited." (PMID 24039755, 2013). "We and others have previously associated CDH17 with hepatocellular carcinoma (HCC)." (PMID 24039755, 2013). "Human CDH17 is only expressed in normal adult intestine, but is re-expressed in stomach, pancreatic and hepatocellular carcinomas." (PMID 38263178, 2024). "Another study showed that targeting CDH17 inhibited tumor growth through the inactivation of the Wnt signaling pathway in hepatocellular carcinoma." (PMID 39617741, 2024). "Previous studies found that targeting CDH17 inactivates Wnt/β-catenin signaling in hepatocellular carcinoma." (PMID 23554857, 2013). "Indeed, CDH17 was described to activate the Wnt/β-catenin signaling pathway in hepatocellular carcinoma." (PMID 38263178, 2024). "A recent study in HCC cells found that depletion of CDH17 resulted in the inhibition of invasion, growth and metastasis in MHCC97H hepatocellular carcinoma cells." (PMID 23554857, 2013). "Aberrant expression of CDH17 has been reported in a number of cancers including GC, CRC, esophageal cancer, hepatocellular carcinoma (HCC), pancreatic cancer (PC) and neuroendocrine tumor (NET)." (PMID 36435809, 2022). "Moreover, upregulation of cancer-specific isoforms of TP73, CDH17, KLF6, FGFr2, FGFR3, DNMT3b3, and OPN has been reported in human hepatocellular carcinoma (HCC) and promoted cell cycle progression, proliferation, invasion and metastasis." (PMID 35463320, 2022).
pancreatic cancer (16 papers, 2015 to 2025). "Having demonstrated that IR700@Nb289‐OMVs plus NIR can significantly suppress and induce the ICD of CDH17‐positive colorectal and pancreatic cancers, we next comprehensively explored the underlying mechanisms involved." (PMID 40240911, 2025). "To investigate the influence of CDH17 on human pancreatic cancer (PC), we performed gain and loss of CDH17 function with siRNA and recombinant plasmid to evaluate its impact on PC cell proliferation, colony formation, and migration." (PMID 31516924, 2019). "Cadherin-17 is reportedly overexpressed in liver, stomach, intestinal, and pancreatic cancers, and the increased expression is associated with the occurrence of metastasis." (PMID 28197418, 2017). "In vivo experiments revealed that this engineered bacterial system exhibited excellent tumor targeting and penetration effects in CDH17‐positive solid tumors, including desmoplastic stroma‐enriched pancreatic cancer." (PMID 38888519, 2024). "The positive rates for CDH17 were 77.4%, 75.9%, and 63.8% in gastric, colorectal, and pancreatic cancers, respectively, indicating CDH17 as a potential target for cancer therapy." (PMID 38888519, 2024). "We have demonstrated that biohybrid bacteria Nb289‐MG1655‐CR can effectively penetrate CDH17‐expressing gastric and pancreatic tumors transplanted in immunocompromised mice." (PMID 38888519, 2024). "In our previous study, we reported liver-intestine cadherin (CDH17) as a novel target in pancreatic cancer." (PMID 36015256, 2022). "CDH17 targeted NIR-PIT inhibited tumor growth in a xenograft model which used a pancreatic cancer cell line." (PMID 36405499, 2021). "Data presented in this article are related to the research article entitled “Disruption of oncogenic liver-intestine cadherin (CDH17) drives apoptotic pancreatic cancer death”." (PMID 31516924, 2019). "Additionally, it would be worthwhile to evaluate the response of a pancreatic cancer model with high CDH17 expression in immunocompetent mice to bacteria‐mediated PTT combined with CD47 nanobody." (PMID 38888519, 2024). "Therefore, Nb289‐engineered MG1655 holds great promise for the treatment of CDH17‐overexpressing tumors, including pancreatic cancer." (PMID 38888519, 2024). "In vitro and in vivo experiments using pancreatic cancer cell lines have demonstrated that CDH-17-targeted NIR-PIT could induce specific cytotoxicity against CDH-17-expressing cells and inhibit tumor progression in a xenograft model of pancreatic cancer." (PMID 35453596, 2022). "This suggested that CDH17-targeted NIR-PIT was a possible treatment in pancreatic cancers." (PMID 35453596, 2022). "Therefore, some initial studies restricted to aggressive and poorly-differentiated colorectal and pancreatic carcinomas observed negligible amounts of CDH17 and presumed that CDH17 was generally reduced in advanced colorectal and pancreatic cancer." (PMID 31324051, 2019). "Additionally, to extend our findings, we explored whether IR700@Nb289‐OMVs plus NIR could effectively regress tumour progression in another CDH17‐positive tumour model induced by the pancreatic cancer cell line Panc02." (PMID 40240911, 2025). "Furthermore, to enhance the tumor‐targeting ability of bacteria, we isolated nanobodies that specifically recognize cadherin 17 (CDH17) protein, which is highly expressed on the membranes of gastrointestinal (GI) cancer cells in gastric, colorectal, and pancreatic cancers." (PMID 38888519, 2024). "We demonstrated that the biohybrid bacteria (Nb289‐MG1655‐CR) specifically accumulated in CDH17‐positive tumors, including fibrotic pancreatic cancer, and significantly inhibited tumor growth without evident side effects after a single administration and one‐time irradiation." (PMID 38888519, 2024). "Thus, some combination of antibody conjugates engaging CEA, CDH17, TROP2, and EGFR might be successful in pancreatic cancer." (PMID 36405499, 2021).
colon cancer (11 papers, 2010 to 2024). "As a final demonstration of its utility, the AAPL approach was applied to map the interactors of liver–intestine-cadherin (CDH17) in colon cancer cells." (PMID 35685794, 2022). "In colon cancer cells, cadherin-17 has been found to interact with α2β1-integrin to regulate cell proliferation." (PMID 26588252, 2015). "We next investigated the biological processes that might underlie the clinical prognostic significance of CDH17 and LRP2, respectively, in stage II colon cancer." (PMID 36612154, 2022). "In addition, overexpression of at least two peptides corresponding to CD166, CD44, CD29, CEACAM5, biglycan, and cadherin 17 was detected in the colon tumour spheres." (PMID 20332776, 2010). "Regarding expression in colon cancer cell lines, KM12SM and HCT116 exhibited high levels of DSC1, while CDH17 was more abundant in the epithelial cell lines KM12SM and HT-29." (PMID 38263178, 2024). "According to such parameters, six cancer-specific proteins in colon cancer (CEACAM8, CDH17, GLOD5, PPM1E, TRIM16, EPCAM), one in breast cancer (CCR9) and none in prostate cancer were identified." (PMID 36243758, 2022). "According to such additional filter, six cancer-specific proteins in colon cancer (CEACAM8, CDH17, GLOD5, PPM1E, TRIM16, EPCAM) and one in breast cancer (CCR9) were identified." (PMID 36243758, 2022). "Moreover, cadherin-17 was shown to modulate α1β2 integrin signaling to induce specific focal adhesion kinase and Ras activation and led to the increase in cell adhesion and proliferation in colon cancer cells and the RGD motif in cadherin-17 was important in this process." (PMID 28197418, 2017).
gastric adenocarcinoma (9 papers, 2004 to 2025). "Additionally, we confirmed CDH17 expression on the cell surface of stomach adenocarcinoma (STAD-IM95 and MKN45) and pancreatic adenocarcinoma (PAAD-ASPC1) cell lines." (PMID 40487639, 2025). "Collectively, the upregulation of two CDX2-dependent genes, CDH17 and DEFA5, found in group 2, represents a characteristic of intestinal cellular lineage that is, in the stomach, implicated in the pathogenesis of intestinal-type gastric adenocarcinoma." (PMID 14710232, 2004).
lymph node metastasis (9 papers, 2007 to 2025). "Our results indicated a statistically significant association between high CDH17 immunohistochemical expression in the tumor core/tumor emboli/lymph node metastasis and the adenocarcinoma NOS histological type." (PMID 40725206, 2025). "These inconsistencies can be supplemented by an investigation focusing on serum CDH17 levels, which report correlations with lymph node metastasis and clinical stage." (PMID 40725206, 2025). "CDH17 hyperexpression, low stage, less number of lymph node metastases, and intestinal or mixed type histology were independent markers for better prognosis (p <0.05)." (PMID 27580354, 2016). "In CDH17 positive cases, the expression level of CDH17 has positive correlation with lymph node metastasis." (PMID 24465527, 2014). "From this perspective, our data are inconsistent with other studies analyzing CDH17 immunohistochemical expression, which show an association between low CDH17 and LVI, lymph node metastasis, and advanced stage, or between high CDH17 and distant metastases and advanced stage." (PMID 40725206, 2025).
breast carcinoma (7 papers, 2014 to 2022). "In addition, we reported the interaction of CDH5 with α2β1 integrin in melanoma and breast cancer cells to activate the integrin signaling pathway, promoting migration and invasion and, consequently, metastasis in a similar way to CDH17." (PMID 31324051, 2019). "In this study, we concluded that the expression of cadherin-17 promotes the metastatic activity of bone marrow metastatic breast cancer cells and that cadherin-17 may be a useful marker of bone marrow metastasis in breast cancer." (PMID 28197418, 2017). "Examination of cadherin 17 expression in human breast cancer tissues may be useful to detect a therapeutic target for future research." (PMID 28197418, 2017). "Thus expression of cadherin-17 clearly enhances the metastatic activity of breast cancer cells in our model." (PMID 28197418, 2017). "However, little is known about the actions of cadherin-17 in breast cancer metastasis." (PMID 28197418, 2017). "Taken together, these findings suggest that expression of cadherin-17 promotes the metastatic activity of the highly bone marrow metastatic breast cancer cells in our model, and that cadherin-17 expression may be a useful marker of bone marrow metastasis in breast cancer." (PMID 28197418, 2017).
lung carcinoma (5 papers, 2018 to 2025). "Utilizing the TCGA database, we also revealed that elevated CDH17 expression in lung cancer tissues was associated with advanced disease progression and reduced patient survival." (PMID 39994505, 2025). "Analysis of the TCGA database revealed that, compared with that in normal lung tissue, the expression level of CDH17 in lung cancer tissue was substantially higher and was positively correlated with the clinical stage of lung cancer." (PMID 39994505, 2025). "Importantly, patients with lung cancer with elevated CDH17 expression in tumor tissues had poorer survival outcomes." (PMID 39994505, 2025). "While the role of CDH17 in the biology of gastrointestinal malignancies is well documented, its role in lung cancer biology has not been well established." (PMID 29899869, 2018). "However, the role of CDH17 and the Hippo signaling pathway in the proliferation, metastasis, and drug resistance of CTC clusters in lung cancer has not been fully explored." (PMID 39994505, 2025).
neuroendocrine tumors (5 papers, 2017 to 2025). "Previous studies have proven that CDH17 is a highly sensitive marker of gastrointestinal adenocarcinoma and neuroendocrine tumors, and is rarely expressed in other tissues." (PMID 28969003, 2017). "Furthermore, CDH17 chimeric antigen receptor T cells have also been found to effectively eradicate CDH17-expressing neuroendocrine tumors and gastric, pancreatic and CRCs in either tumor xenograft or autochthonous mouse models." (PMID 38608841, 2024). "However, CDH17 is expressed in some NSCLS, neuroendocrine tumors of bronchi, and endometrioid carcinoma." (PMID 28969003, 2017).
adenoma (4 papers, 2004 to 2022). A neoplasm arising from the epithelium. "Recent studies reported that CDH17 was a highly sensitive marker for bladder cancer and was positively expressed in 81% of metanephric adenomas." (PMID 28969003, 2017). "RACK1, ACBP, CDH17 and EEF1G were significantly overexpressed in low-grade adenomas, whereas DEFA5 was significantly overexpressed in high-grade adenomas and suppressed in adenocarcinomas." (PMID 14710232, 2004).
colorectal adenocarcinoma (4 papers, 2017 to 2024). The most common type of colorectal carcinoma. "Cadherin-17 (CDH17) and SATB homeobox 2 (SATB2) immunoexpression have recently been demonstrated in colorectal adenocarcinoma." (PMID 28969003, 2017). "The combination of CK7+/CDX-2+ was reported to have a high sensitivity (71.3%) and specificity (82%) in differential diagnosis of PEAC from colorectal adenocarcinoma, while combining cadherin-17 (negative) and SATB homeobox 2 (negative) also showed high sensitivity (77.0%) and specificity (100%)." (PMID 35172862, 2022). "Going forward, gastric and colorectal adenocarcinomas may be the indications in which [89Zr]Zr-DFO-D2101 will have the most utility, as patients with each have been shown to express CDH17, and both cancers are plagued by a lack of reliable radiotheranostics." (PMID 38625402, 2024).
metastatic colorectal cancer (4 papers, 2019 to 2025). "In addition, we have observed a large effect of CDH17 on cell adhesion and proliferation in metastatic colorectal cancer cell lines." (PMID 31324051, 2019).
metastatic disease (4 papers, 2017 to 2025). "High levels of CDH17 have been linked to metastatic disease and poor prognoses in patients with these malignancies, fueling interest in the protein as a target for diagnostics and therapeutics." (PMID 38625402, 2024). "Given the maintenance of high expression of CDH17 in metastatic CRC, future studies should investigate the potential of CDH17 Nb-based NIR-II probes for imaging metastatic CRC tissues and direct the imaging-guided metastatic tumor removal." (PMID 38911825, 2024). "The upregulation of genes encoding matrix associated factors including proteases and cell adhesion molecules such as ADAM12, NTN3, LRRC15, CDH17, PCDH19, VTN highlighted the relevance of the tumor microenvironment and cell–cell and cell–matrix interaction for progression to metastatic disease." (PMID 41402347, 2025).